RNU6-838P (RNA, U6 small nuclear 838, pseudogene)
Gene: Small nuclear RNA gene on chromosome 4 (48,106,081 to 48,106,188, reverse strand). Ensembl gene ENSG00000200269.
Homologues: Orthologues: chimpanzee U6 (99% identical), macaque U6 (94% identical), guinea pig U6 (90% identical), mouse Gm25670 (89% identical), guinea pig U6 (82% identical). Paralogues in human: RNU6-1011P (89% identical), RNU6-12P (89% identical), RNU6-13P (89% identical), RNU6-32P (89% identical), RNU6-38P (89% identical), RNU6-41P (89% identical), RNU6-1 (88% identical), RNU6-15P (88% identical), RNU6-17P (88% identical), RNU6-18P (88% identical), RNU6-2 (88% identical), RNU6-31P (88% identical), and 1285 more.